ENSG00000276418 (novel protein, TPD52-MRPS28 readthrough)
Gene: Protein-coding gene on chromosome 8 (79,918,860 to 80,080,775, reverse strand). Ensembl gene ENSG00000276418.
Genetic constraint (gnomAD): Missense variants: 249 observed, 287.93 expected, observed/expected ratio (o/e) 0.86, 90% interval 0.78 to 0.96. Synonymous variants: 103 observed, 108.27 expected, observed/expected ratio (o/e) 0.95, 90% interval 0.81 to 1.12.